SGPP1 (sphingosine-1-phosphate phosphatase 1)
Description:
Specifically dephosphorylates sphingosine 1-phosphate (S1P), dihydro-S1P, and phyto-S1P. Does not act on ceramide 1-phosphate, lysophosphatidic acid or phosphatidic acid. Sphingosine-1-phosphate phosphatase activity is needed for efficient recycling of sphingosine into the sphingolipid synthesis pathway. Regulates the intracellular levels of the bioactive sphingolipid metabolite S1P that regulates diverse biological processes acting both as an extracellular receptor ligand or as an intracellular second messenger. Involved in efficient ceramide synthesis from exogenous sphingoid bases. Converts S1P to sphingosine, which is readily metabolized to ceramide via ceramide synthase. In concert with sphingosine kinase 2 (SphK2), recycles sphingosine into ceramide through a phosphorylation/dephosphorylation cycle (By similarity). Regulates endoplasmic-to-Golgi trafficking of ceramides, resulting in the regulation of ceramide levels in the endoplasmic reticulum, preferentially long-chain ceramide species, and influences the anterograde membrane transport of both ceramide and proteins from the endoplasmic reticulum to the Golgi apparatus. The modulation of intracellular ceramide levels in turn regulates apoptosis (By similarity). Via S1P levels, modulates resting tone, intracellular Ca(2+) and myogenic vasoconstriction in resistance arteries. Also involved in unfolded protein response (UPR) and ER stress-induced autophagy via regulation of intracellular S1P levels. Involved in the regulation of epidermal homeostasis and keratinocyte differentiation (By similarity).
Synonyms: SPPase1; SPP-1
Tractability: Antibody: UniProt places it where antibodies can reach, with medium confidence; UniProt predicts a signal peptide or a membrane-spanning region; its Gene Ontology location is reachable by antibodies, with medium confidence. PROTAC: ubiquitination databases record sites on it; its protein half-life has been measured.
Gene: Protein-coding gene on chromosome 14 (63,684,216 to 63,728,065, reverse strand). Ensembl gene ENSG00000126821.
Subcellular location: Endoplasmic reticulum membrane; Cell membrane
Subcellular location (Human Protein Atlas): Nucleoplasm
Pathways (Reactome):
Metabolism: Sphingolipid catabolism
Gene Ontology:
Molecular function: dihydrosphingosine-1-phosphate phosphatase activity; sphingosine-1-phosphate phosphatase activity
Biological process: ER to Golgi ceramide transport; phospholipid dephosphorylation; regulation of epidermis development; regulation of keratinocyte differentiation; sphingolipid catabolic process; sphingosine metabolic process
Cellular component: endoplasmic reticulum membrane; nucleoplasm; plasma membrane; endoplasmic reticulum; membrane
Genetic constraint (gnomAD): Loss-of-function variants: 17 observed, 22.53 expected, observed/expected ratio (o/e) 0.75, 90% interval 0.51 to 1.13. The upper end of that interval is the gene's LOEUF score, 1.13, which puts it in group 4 of 6, group 1 being the genes least tolerant of losing a copy. Missense variants: 498 observed, 504.12 expected, observed/expected ratio (o/e) 0.99, 90% interval 0.92 to 1.06. Synonymous variants: 226 observed, 200.57 expected, observed/expected ratio (o/e) 1.13, 90% interval 1.01 to 1.26.
Homologues: Orthologues: chimpanzee SGPP1 (99% identical), macaque SGPP1 (98% identical), dog SGPP1 (90% identical), pig SGPP1 (89% identical), rat Sgpp1 (80% identical), mouse Sgpp1 (80% identical), guinea pig SGPP1 (69% identical), tropical clawed frog sgpp1 (61% identical), zebrafish sgpp1b (56% identical), zebrafish sgpp1a (46% identical), Drosophila melanogaster CG31717 (9% identical), Caenorhabditis elegans T13C5.6 (7% identical). Paralogues in human: SGPP2 (32% identical), PLPP7 (10% identical), PLPP6 (10% identical).